PRAMEF7 (PRAME family member 7)
Tractability: PROTAC: ubiquitination databases record sites on it.
Gene: Protein-coding gene on chromosome 1 (12,916,610 to 12,920,751, forward strand). Ensembl gene ENSG00000204510.
Gene Ontology:
Molecular function: ubiquitin-like ligase-substrate adaptor activity
Biological process: proteasome-mediated ubiquitin-dependent protein catabolic process; negative regulation of apoptotic process; negative regulation of cell differentiation; negative regulation of DNA-templated transcription; positive regulation of cell population proliferation
Cellular component: Cul2-RING ubiquitin ligase complex; cytoplasm
Genetic constraint (gnomAD): Loss-of-function variants: 0 observed, 3.91 expected, observed/expected ratio (o/e) 0, 90% interval 0 to 0.76. That is too few expected variants to judge how well the gene tolerates losing a copy. Missense variants: 2 observed, 79.91 expected, observed/expected ratio (o/e) 0.025, 90% interval 0.009 to 0.079. Synonymous variants: 1 observed, 29.91 expected, observed/expected ratio (o/e) 0.0334, 90% interval 0.011 to 0.16.
Homologues: Orthologues: mouse Pramel12 (48% identical), rat Pramef8 (47% identical), mouse Pramel13 (47% identical), rat Pramef12 (46% identical), mouse Gm13040 (45% identical), mouse Gm13043 (45% identical), mouse Gm13057 (45% identical), mouse Pramel31 (44% identical), mouse Pramel20 (44% identical), mouse Pramel15 (44% identical), mouse Pramel16 (44% identical), mouse Pramel43 (43% identical), and 78 more. Paralogues in human: PRAMEF8 (99% identical), PRAMEF12 (84% identical), PRAMEF6 (63% identical), PRAMEF5 (63% identical), PRAMEF15 (62% identical), PRAMEF20 (62% identical), PRAMEF9 (62% identical), PRAMEF25 (62% identical), PRAMEF26 (62% identical), PRAMEF27 (62% identical), PRAMEF11 (61% identical), PRAMEF4 (61% identical), and 12 more.